NPIPB2 (nuclear pore complex interacting protein family member B2)
Tractability: PROTAC: ubiquitination databases record sites on it.
Gene: Protein-coding gene on chromosome 16 (11,927,259 to 11,976,643, reverse strand). Ensembl gene ENSG00000234719.
Subcellular location: Nucleus
Subcellular location (Human Protein Atlas): Nucleoplasm
Gene Ontology:
Cellular component: nucleus
Genetic constraint (gnomAD): Loss-of-function variants: 19 observed, 21.16 expected, observed/expected ratio (o/e) 0.9, 90% interval 0.63 to 1.32. The upper end of that interval is the gene's LOEUF score, 1.32, which puts it in group 5 of 6, group 1 being the genes least tolerant of losing a copy. Missense variants: 339 observed, 312.4 expected, observed/expected ratio (o/e) 1.09, 90% interval 0.99 to 1.19. Synonymous variants: 111 observed, 104.23 expected, observed/expected ratio (o/e) 1.06, 90% interval 0.91 to 1.25.
Homologues: Paralogues in human: NPIPB5 (78% identical), NPIPB11 (78% identical), NPIPB12 (78% identical), NPIPB4 (78% identical), NPIPB13 (77% identical), NPIPB15 (69% identical), NPIPB6 (69% identical), NPIPB8 (68% identical), NPIPB9 (68% identical), NPIPA5 (68% identical), NPIPA6 (68% identical), NPIPA9 (68% identical), and 7 more.